RNA5SP531 (RNA, 5S ribosomal pseudogene 531)
Gene: Ribosomal RNA gene on chromosome 8 (48,316,669 to 48,316,770, forward strand). Ensembl gene ENSG00000277418.
Homologues: Orthologues: chimpanzee 5S_rRNA (100% identical). Paralogues in human: RNA5SP150 (53% identical), RNA5S1 (52% identical), RNA5S10 (52% identical), RNA5S11 (52% identical), RNA5S12 (52% identical), RNA5S13 (52% identical), RNA5S14 (52% identical), RNA5S15 (52% identical), RNA5S16 (52% identical), RNA5S17 (52% identical), RNA5S2 (52% identical), RNA5S3 (52% identical), and 26 more.